ERBB3 (erb-b2 receptor tyrosine kinase 3)
Diseases named in the same sentence as ERBB3 in open-access papers (continued):
Sharing a sentence is not in itself a finding about the gene and the disease.
breast cancer (continued). "Herein, we investigate the antitumor activity of MM-121/SAR256212, a fully human anti-erbB3 antibody (Ab), against two erbB2-overexpressing breast cancer cell lines resistant to trastuzumab." (PMID 24215614, 2013). "Co-expression of erbB3 and erbB2 is frequently observed in breast cancers and breast cancer cell lines, and erbB3 plays an important role in breast cancer development driven by erbB2 amplification/overexpression." (PMID 24215614, 2013). "We have reported that elevated expression of erbB3 confers paclitaxel resistance in erbB2+ breast cancer cells via a PI-3K/Akt-dependent mechanism." (PMID 24215614, 2013). "It has been shown that erbB3 serves as a critical co-receptor of erbB2, and its expression is a rate-limiting factor for erbB2-induced breast cancer cell survival and proliferation." (PMID 24215614, 2013). "Our previous studies indicated that elevated expression of erbB3 led to paclitaxel resistance in erbB2-overexpressing breast cancer cells via PI-3 K/Akt signaling-dependent upregulation of Survivin." (PMID 24168763, 2013). "We believe that MM-121 will exhibit therapeutic potential in all erbB2-positive breast cancer patients (not only those with strong erbB3-expressing tumors) as long as the tumors show active erbB3 signaling." (PMID 24168763, 2013). "It often interacts with other receptor tyrosine kinases (RTKs), such as erbB3, to activate the oncogenic signaling, like PI-3K/Akt pathway, in breast cancers." (PMID 24215614, 2013). "Elevated expression of erbB3 rendered erbB2-overexpressing breast cancer cells resistant to paclitaxel via PI-3 K/Akt-dependent upregulation of Survivin." (PMID 24168763, 2013). "We demonstrate that targeting of erbB3 with the blocking Ab MM-121 significantly enhances paclitaxel antitumor activity against erbB2-overexpressing breast cancer cells in our in vitro and in vivo models." (PMID 24168763, 2013). "One of its isotypes, HRG-β1, binds to ErbB3 and forms heterodimers with other ErbB family members, thereby enhancing the proliferation and tumorigenesis of breast cancer cells." (PMID 23937725, 2013). "A report showed that ErbB2/HER2 and ErbB3/HER3 were both targets of miR-125b in breast cancer SKBr3 cells." (PMID 22523546, 2012). "In fact, inhibition of HER2 phosphorylation by TKIs targeting EGFR and HER2 in HER2+ breast cancer cells is followed by feedback upregulation of activated ErbB3." (PMID 22889873, 2012). "The analysis of human tumor biopsies revealed a significant correlation between α6β4 integrin/ErbB-3/phosphorylated-AKT signaling axis in ERbeta1-negative breast cancers derived from patients with lower disease-free survival." (PMID 22567280, 2012). "V-erb-b2 erythroblastic leukemia viral oncogene homolog 3 (ERBB3) is a direct target of miR-148a in human breast cancer cells through direct binding of miR-148a to ERBB3 3′-UTR region." (PMID 23554686, 2011). "There is also growing awareness of the importance of the erbB2/erbB3 heterodimer in breast cancer progression." (PMID 21939528, 2011). "ErbB3 signalling promotes resistance to tyrosine kinase inhibition in breast cancer cells via heterodimerisation with ErbB2." (PMID 21792199, 2011). "IRS-1 can be recruited to IGF-IR and erbB3 in ER+ breast cancer cells, and this provides an adaptive resistance mechanism when these receptors are targeted individually." (PMID 21939528, 2011). "For example, both ErbB3 and ErbB4 have been found to localise not only at the membrane but also within the nucleus in breast cancer cells." (PMID 21396094, 2011). "Western blot analysis demonstrated that both basal and HRGβ1-primed IRS-1 Y612 and Y896 phosphorylation levels were markedly reduced following incubation of MCF-7 and T47D breast cancer cells with siRNA-targeting erbB3 protein expression." (PMID 21939528, 2011). "Enforced expression of miR-205 was shown to inhibit cell invasion and suppress lung metastasis of breast cancer cells in nude mice, possibly through targeting ErbB3." (PMID 21426561, 2011).
breast cancer (continued). "This information would be helpful for targeting the miR-148a/ERBB3 pathway for breast cancer prevention and treatment in the future." (PMID 23554686, 2011). "Consistent with ERBB3 inhibition, forced expression of miR-148a in breast cancer cells inhibited the activation of ERBB3 downstream molecules including AKT, ERK1/2, and p70S6K1." (PMID 23554686, 2011). "ERBB3 is involved in regulating cancer initiation, tumor metastasis and angiogenesis and is important in breast cancer development." (PMID 23554686, 2011). "It has been shown that FAK is essential for ErbB2/ErbB3-induced oncogenesis and breast cancer invasion." (PMID 21034468, 2010). "ErbB3 is often overexpressed in human breast cancers, frequently in conjunction with overexpression of the proto-oncogene ErbB2/HER2." (PMID 20492690, 2010). "The EGFR and ERBB3 are overexpressed in 50–70% of lung, colon and breast carcinoma; ERBB2 is overexpressed in 30% of breast cancer patients; ERBB4 is expressed in 50% of breast cancer patients and 22% of colon cancer patients." (PMID 20010942, 2010). "The receptor ErbB3/HER3 is often over-expressed in human breast cancers, frequently in conjunction with over-expression of the proto-oncogene ERBB2/HER2/NEU." (PMID 19019207, 2008). "We first evaluated the expression level of ERα and ERβ, β4 integrin subunit, ErbB2, and ErbB-3 in a series of human mammary tumor cell lines including MDA-MB 231, MDA-MB 361, SKBr3, BT474, BT549, and T47D." (PMID 18270579, 2008). "We provided evidence that a strong relationship occurs between α6β4 and ErbB-3 positivity in ERβ1-negative breast cancers." (PMID 18270579, 2008). "As expected, this list contains numerous markers of breast cancer cells whose expression specificity was previously reported by other (notably ERBB3, XBP1, KRT18, IL6ST, CREB1, TFF1, TFF3)." (PMID 19104654, 2008). "Mammary tumours from transgenic mice expressing activated mutants of ErbB2 also express elevated levels of total and tyrosine-phosphorylated ErbB2 and ErbB3." (PMID 18700973, 2008). "Collectively, these data indicate a role of ErbB-3 protein in the mechanisms that regulate the invasion of mammary tumor cells." (PMID 18270579, 2008). "The analysis of human tumors revealed a significant relationship between α6β4 and ErbB-3 in P-Akt-positive and ERβ1-negative breast cancers derived from patients with lower disease free survival." (PMID 18270579, 2008). "ErbB2, a member of the epidermal growth factor receptor (EGFR) family, is overexpressed in 20% to 30% of human breast cancer cases and forms oncogenic signalling complexes when dimerised to ErbB3 or other EGFR family members." (PMID 18700973, 2008). "It targets ERBB2 and ERBB3 in human breast cancer cell lines and its depletion is critical for the proliferation of differentiated cells." (PMID 18478077, 2008). "Protein levels of ErbB3 and tyrosine phosphorylation of ErbB3 are increased in mammary tumours from transgenic mice expressing activated ErbB2 (Neu-DL), suggesting that ErbB2 and ErbB3 function as an oncogenic unit." (PMID 18700973, 2008). "ErbB3 overexpression has been noted in breast cancer for some time, but the aetiologic and prognostic role of ErbB3 in breast carcinogenesis has only recently been widely recognised." (PMID 18283314, 2008). "Although the prognostic/predictive value of ErbB3 expression in breast cancer is unclear, ErbB3 is known to contribute to therapeutic resistance." (PMID 19019207, 2008). "The ErbB3 growth factor receptor is being increasingly recognised as a central player in ErbB2-driven breast cancer." (PMID 18841159, 2008). "In mammary carcinoma cells, we evidenced that the α6β4 integrin strongly influence Akt phosphorylation through ErbB-3 protein regulation." (PMID 18270579, 2008). "We found higher levels of expression of ErbB1 and lower levels of SSTR1, SSTR4 and ErbB3 in ERα – (MDA-MB-231) cells when compared to ER+ (MCF-7) breast cancer cells." (PMID 16519802, 2006).
breast cancer (continued). "The co-expression of erbB3 with erbB2 in both the activated and wt-neu/ErbB2 transgenic model systems suggested a biological role for erbB3 in mammary tumor pathogenesis." (PMID 16168116, 2005). "Immunohistochemical and Western blot analyses were performed to study the expression of rat c-neu/ErbB2 and mouse erbB3 in mammary tumors and tumor-derived cell lines from the wt rat c-neu transgenic mice." (PMID 16168116, 2005). "In aggregate, these data suggest that HRG induces activation of both MEK/MAPK and PI-3K/Akt signaling transduction pathways in mammary tumor cells with elevated expression levels of both the transgene rat c-neu/ErbB2 and the endogenous mouse ErbB3 gene." (PMID 16168116, 2005). "In contrast, a recent publication reported its up-regulation in breast cancer, suggesting a dual role of ERBB3 in cell cycle regulation." (PMID 16001974, 2005). "We have shown that transgenic mice bearing the wt-rat c-neu gene, under control of the MMTV promoter, develop mammary tumors that overexpress the rat c-neu transgene and the endogenous mouse erbB3 protein, in the vast majority of cases." (PMID 16168116, 2005). "Co-expression of several receptor tyrosine kinases (RTKs), including erbB2 and erbB3, is frequently identified in breast cancers." (PMID 16168116, 2005). "Mammary tumors and tumor-derived cell lines frequently exhibited elevated co-expression of erbB2 and erbB3." (PMID 16168116, 2005). "Human breast cancer cell lines commonly co-overexpress both erbB2 and erbB3, further supporting their role in breast carcinogenesis." (PMID 16168116, 2005). "HRG strongly stimulated the proliferation of three of the four mouse mammary tumor cell lines (78617, 85815, 85819) with overexpression of both erbB2 and erbB3." (PMID 16168116, 2005). "Our results indicate that over-expression of endogenous mouse erbB3 plays an important role in the development and progression of mammary tumors that arise in mice bearing the wt-rat c-neu transgene." (PMID 16168116, 2005). "Expression of c-erbB3 protein was investigated in 104 primary breast carcinomas comprising nine comedo ductal carcinoma in situ (DCIS), 91 invasive ductal carcinomas and four invasive lobular carcinomas using two monoclonal antibodies, RTJ1 and RTJ2." (PMID 9823984, 1998). "Additionally, hsa-miR-143 has been found to suppress cell proliferation and invasion in breast cancer by targeting ERBB3." (PMID 40468582, 2025). "Phagocytosis by resident macrophages or microglia is likely to be negligible as these cells express low to undetectable ErbB3 RNA compared with breast cancer cells and may comprise 2.5% or less of the tumour cell population." (PMID 39984637, 2025). "Since the interaction between NRG1 and ERBB3 is critical for tumor growth, understanding the molecular mechanisms underlying NRG1–ERBB3 complex formation is essential for elucidating diabetes-assisted breast cancer progression." (PMID 37389721, 2023). "Recent results link high ErbB3 activity with lung and breast cancers." (PMID 37800117, 2023). "Apart from BTK inhibition, ibrutinib also blocks the activation of EGFR, human epidermal growth factor receptor 2 (HER2), Erb-B2 receptor tyrosine kinase 3 (ErbB3), and Erb-B2 receptor tyrosine kinase 4 (ErbB4), which results in increased apoptosis of breast cancer cells." (PMID 36903645, 2023). "Overall, our data suggest that ERBB2/ERBB3 plays an oncogenic role in basal-like/triple-negative breast cancer patients, suggesting its neutralization as a therapeutic strategy for these breast cancer subtypes, which today have very limited treatment opportunities." (PMID 35406375, 2022). "An intriguing development is an ErbB3-targeting antibody-drug conjugate, U3-1402, which has shown encouraging activity in ErbB3-overexpressing breast cancer and EGFR-mutant, EGFR inhibitor-resistant non-small cell lung cancer and would be of interest in combination with cetuximab in HNSCC." (PMID 35625959, 2022).
breast cancer (continued). "Erbb3 shares a similar expression pattern to Grhl2 during breast cancer in the luminal epithelium." (PMID 35269877, 2022). "Intriguingly, higher ERBB3 expression levels correlate with lower relapse-free survival in basal-like/triple-negative (HER2-/ER-/PR-) breast cancer patients, and NRG1/ERBB3/ERBB2 axis was shown to promote anchorage-independent cell growth in basal-like/triple-negative breast cancer cells." (PMID 35664762, 2022). "As expected, we could show that the synthesized and fluorescence-labeled anti-ErbB2-anti-ErbB3-bsFabs exhibited improved fluorescence intensities in mammalian breast cancer cell lines compared with the single Fabs alone." (PMID 35328563, 2022). "Additionally, it has been found that the overexpression of ErbB3 plays a critical role in transforming the activity of other ErbB family members in breast cancer cells." (PMID 35806132, 2022). "In order to assess whether this effect would be retained in vivo, the antitumor effect of dAd/ErbB3 was examined in an MDA-MB-231 human breast cancer xenograft model." (PMID 35806132, 2022). "Similarly, the evaluation of the mRNA expression levels of ERBB3 in breast cancer specimens stratified for clinical subtypes demonstrated that the luminal, HER2+, and triple-negative subgroup display the highest, intermediate and lowest levels, respectively." (PMID 35406375, 2022). "Second, ERBB3 heterodimerization with ERBB2 has been demonstrated to drive oncogenic signaling in breast cancer as the effects of ERBB2 inhibition could be reversed by increasing ERBB3 phosphorylation and activity to drive a TKI resistance phenotype." (PMID 34675407, 2022). "This study aimed to evaluate the role of ERBB3 in different molecular subtypes of breast cancers." (PMID 35406375, 2022). "To verify whether miR-145 directly acted on ERBB3 to affect HER2-positive breast cancer cells, we divided SKBR3 and BT474 cells into 4 groups: si-ctr, si-circESPTI1, si-circESPTI1 + ERBB3-ctr, and si-circESPTI1 + ERBB3." (PMID 36059813, 2022). "In addition, CXCL12 inhibits DPP4 and accelerates EMT and metastasis in breast cancer, and the inhibition of ERBB3 signaling suppresses EMT of hepatocellular carcinoma." (PMID 33463049, 2021). "Previously, an Erbb3 mutant with YXXM-to-FXXM mutations (Erbb37F) was analyzed in a mouse breast cancer model and revealed no embryonic lethality." (PMID 34714866, 2021). "ERBB3 knock‐down in ERBB2‐amplified mammary cancer cells blocked tumor formation." (PMID 36618440, 2021). "Further, tissue‐specific deletion of Erbb3 impaired colon, liver, and mammary tumor development." (PMID 36618440, 2021). "FLG2, FMN2, and ERBB3 have been reported to be related to breast cancer." (PMID 35111673, 2021). "In addition, in HER2- or ERBB2-enriched breast cancer, dimerization with HER3/ERBB3 elicits robust activation of PI3K and Akt, since HER3/ERBB3 possesses six docking sites for PI3K." (PMID 35578699, 2021). "We tested these hypotheses by mining a combined dataset of the three largest primary breast cancer series with data on tumor ERBB2 and ERBB3 mutational status, gene expression, clinicopathological features, and patient survival outcomes." (PMID 32782013, 2020). "However, the activation of ERBB3 mediated by NRG1 reduces the interaction of ERBB3 with PARK7 in breast cancer cells." (PMID 32357493, 2020). "ErbB2 and ErbB3 co-overexpression decreases survival rate of breast cancer patients." (PMID 30621788, 2019). "In addition, functional cooperation of miR-125a, miR-125b, and miR-205 can act together to suppress erbB2/erbB3 expression in breast cancer cells, which manifest a novel breast cancer treatment via miRNA-dependent or -independent mechanisms." (PMID 31301674, 2019). "PTEN downregulation was reported to activate PI3K/Akt pathway which may involve prolonged association between PIK3R1/p85α and the IRS-1 as well as with ErbB3, contributing to the therapy resistance in breast cancers." (PMID 31660072, 2019).
breast cancer (continued). "We have previously found that the class I HDAC inhibitor (HDACi), entinostat (also known as MS-275 or SNDX-275) specifically enhanced expression of miR-125a, miR-125b, and miR-205, which acted in concert to downregulate ErbB2 and ErbB3 in ErbB2-overexpressing breast cancer cells." (PMID 30961642, 2019). "Collectively, our data demonstrated that concomitant expression of the miRNA cluster targeting of erbB3 significantly inhibited proliferation of HER2-overexpressing breast cancer cells, likely via cell cycle G1 arrest as well as inactivation of the HER3 signaling pathways." (PMID 30093840, 2018). "Overexpression of ErbB3 occurs in about 20% of breast cancers." (PMID 30241301, 2018). "For example, HER2 and HER3 (erbB3), which are significantly correlated with decreased disease-specific survival in breast cancer patients, could be suppressed by miR-125a or miR-125b." (PMID 29434522, 2018). "After establishing that ErbB3 signaling on macrophages was important for enhancing breast cancer cell migration across the endothelial cell layer, we then tested whether altering expression of the ErbB3 ligand NRG1 by the cancer cells was important." (PMID 29636067, 2018). "To test this hypothesis, we decided to examine our innovative idea with miR-125a and miR-205, and to determine whether co-expression of the two miRNAs will exert functional cooperation to inhibit erbB3 expression in HER2-overexpressing breast cancer cells." (PMID 30093840, 2018). "Our current studies aim to examine the hypothesis that functional cooperative miRNAs will effectively inhibit erbB3 expression in HER2-overexpressing breast cancer cells." (PMID 30093840, 2018). "Phase 2 clinical data published with anti-ErbB3 mAbs evaluated in lung, ovarian, and breast cancer have suggested that NRG1 expression levels may be a potential biomarker to enrich for patients who will respond to therapy." (PMID 28723928, 2017). "Additionally, in SK-BR-3 and BT-474 breast cancer cell lines with ErbB3 overexpression curcumin inhibited the phosphorylation of Akt and MAPK pathways." (PMID 28286519, 2017). "Indeed, ErbB2 amplification is a hallmark of human breast cancer, and a number of ErbB ligands are highly expressed in breast tumors, including the EGFR ligand TGFα and the ErbB3/ErbB4 ligand HRG." (PMID 27351228, 2016). "Since ErbB2 remained continuously expressed in a panel of breast cancer cell lines treated with either agent, and no substantial increase in internalization nor degradation of ErbB2 was observed, we inspected the phosphostatus of ErbB2 as well as of ErbB3." (PMID 27255951, 2016). "In the present study, we investigated in human breast cancer cells whether a similar mechanism plays a role in the feedback regulation of the ErbB2/ErbB3 heterodimer, the most potent ErbB receptor dimer." (PMID 27531070, 2016). "Notably, we reported that HRG-induced activation of P-Rex1/Rac1 and motility via ErbB3 in breast cancer cells is mediated by transactivation of CXCR4, a G-protein-coupled receptor widely involved in metastatic dissemination." (PMID 27351228, 2016). "Here, we take advantage of the same cell models to determine if the trastuzumab-resistant breast cancer cells become refractory to lapatinib, and to explore whether erbB3- and IGF-1R-initiated signaling pathways differentially modulate lapatinib sensitivity." (PMID 26621843, 2016). "In the present study, we investigated whether similar feedback control is employed for the ErbB2/ErbB3 heterodimer in breast cancer cells." (PMID 27531070, 2016). "Moreover, overexpression of miR-125b inhibited cell growth and reduced migration and invasion in breast cancer cells through suppression of ERBB2 (erythroblastic leukemia viral oncogene homolog 2) and ERBB3 in breast cancer cells." (PMID 25605244, 2015).